EZH2 (enhancer of zeste 2 polycomb repressive complex 2 subunit)
Diseases named in the same sentence as EZH2 in open-access papers (continued):
Sharing a sentence is not in itself a finding about the gene and the disease.
cancer (continued). "Taken together, LSD1, DOT1L, and EZH2 inhibitors have the potential to induce substantial changes in histone methylation, thereby significantly altering the epigenetic landscape of cancer cells." (PMID 40427015, 2025). "EZH2-dependent silencing of TSGs drives oncogenic proliferation, aggressive invasion, and refractory resistance in cancer." (PMID 40927709, 2025). "EZH2 is a critical epigenetic regulator known to be dysregulated across various cancer types, playing a pivotal role in tumorigenesis." (PMID 40314246, 2025). "EZH2, a histone methyltransferase, silences genes by methylating histone H3 at lysine 27 (H3K27), and its overexpression is linked to various cancers." (PMID 39083441, 2025). "The active involvement of EZH2 in a wide spectrum of biological processes justifies its implication in a broad array of diseases including cancer, and neurodegenerative disorders." (PMID 40723311, 2025). "Many studies have demonstrated that the polycomb repressive complex 2 (PRC2)-dependent transcription repression by EZH2 suppresses interferon γ-signaling and promotes PCa cell invasion, cancer stem cell features, and angiogenesis, among others." (PMID 40626556, 2025). "TUG1, a tumor suppressor-like lncRNA, inhibits cancer stem-cell–like properties and tumorigenicity by downregulating EZH2." (PMID 41149459, 2025). "The finding that USP7 interacts with Ezh2 is consistent with previous reports where USP7 was found to interact with and stabilize Ezh2 and that loss of USP7 reduced Ezh2 expression in cancer cells." (PMID 40247205, 2025). "Enhancer of zeste homolog 2 (EZH2) is a frequently upregulated epigenetic factor in human cancers, while deleted in liver cancer 1 (DLC1) is an anticancer gene that is often expressed at low levels or not expressed in many malignancies." (PMID 40989587, 2025). "Given that EZH2 is a driver gene for a number of cancers, the development of EZH2 inhibitors has become an active field." (PMID 41372608, 2025). "Although the significance of blocking EZH2 in cancer for inhibiting cancer progression is widely recognized, the clinical application of EZH2 inhibitors continues to encounter numerous challenges." (PMID 40028035, 2025). "EZH2 plays a critical role in maintaining stem cell self‐renewal and in cancer initiation and progression." (PMID 40904706, 2025). "EZH2 is aberrantly expressed in a variety of malignant tumors; therefore, EZH2 is an appropriate therapeutic target." (PMID 40346993, 2025). "EZH2 is frequently dysregulated in many cancer cell types, contributing to uncontrolled cell proliferation and tumourigenesis." (PMID 40310411, 2025). "For instance, biomarkers such as EZH2 (high-risk) and CD34 (protective) would benefit from validation against GTEx-derived normal cervical tissue expression to confirm their cancer-specific dysregulation." (PMID 40678068, 2025). "Our work highlights novel roles for mutant-EZH2 in lymphomagenesis and establishes new concepts for measuring epigenetic heterogeneity and intra-chromatin connectivity in cancer cells." (PMID 40504770, 2025). "EZH2, which promotes carcinogenesis and is highly expressed in a myriad of human cancers, serves as a perfect target for cancer therapy." (PMID 40310411, 2025). "Intriguingly, DLBCL patients also exhibit recurrent loss of KMT2D in combination with EZH2 GOF, yet the composite effects of these mutations on the epigenetic network and the cancer phenotype are not well understood." (PMID 40504770, 2025). "We thus propose that cPLA2α activity regulates transcriptional repression by EZH2 to protect cancer cells that are reliant on fatty acids as an energy source." (PMID 39747052, 2025). "Specifically, its association with EZH2, the catalytic subunit of the PRC2 complex, has been demonstrated in cancers such as pancreatic cancer and castration-resistant prostate cancer." (PMID 41221298, 2025).
cancer (continued). "Our study demonstrated that squamocin effectively suppresses the functions of the EZH2/MYC axis across multiple cancer types." (PMID 39823459, 2025). "Curcumin, a compound derived from turmeric, is well-known for its anti-cancer properties, and recent studies have shown that it can inhibit various HMTs, including EZH2." (PMID 41335282, 2025). "The dual function of EZH2 in different tissues and cancers exemplifies the complexity of the role of epigenetic alterations in cancer." (PMID 37828086, 2025). "Fourth, ARID1A‐depleted cancer cells are more sensitive to the enhancer of zeste homolog 2 methyltransferase (EZH2) inhibitors because ARID1A and EZH2 are functionally antagonistic in the control of gene expression." (PMID 40621620, 2025). "The results were consistent with those from TCGA database, showing that EZH2 expression was elevated in cancer tissues relative to normal tissues, with an AUC of 0.954, and high expression of EZH2 was associated with poor prognosis." (PMID 41298718, 2025). "Downregulation of EZH2 expression or the topical administration of EZH2 inhibitors has been observed to provide relief for neuropathic and cancer pain." (PMID 40787071, 2025). "Cancers with high expression of the ES signature often show high expression of the PRC2 core components EZH2 and EED." (PMID 40678543, 2025). "The polycomb repressive complex 2 (PRC2) member EZH2 is the main enzyme for methylating H3K27 residues in cancer, leading to gene silencing." (PMID 40722046, 2025). "EZH2 upregulation disrupts normal methylation patterns, silences tumor suppressor genes, promotes cell proliferation and invasion, and accelerates cancer progression." (PMID 40959108, 2025). "Highlighting a promising therapeutic avenue for integrating EZH2 inhibitors into immune-checkpoint-based cancer therapy." (PMID 41335282, 2025). "We then investigated the expression of some methyltransferases involved in the survival of cancer cells, such as EZH2, G9a, MLL1, and SET7/9, in HCT116 and SW480 cells undergoing curcumin treatment." (PMID 39860204, 2025). "Studies have implicated epigenetic and transcriptional silencing of MHC-I expression, such as through increased histone methylation mediated by proteins like EZH2, in the development and progression of many types of human cancers." (PMID 41252204, 2025). "EZH2 stimulates gene transcription in cancer cells and has been found to be overexpressed in a wide array of cancers." (PMID 40534232, 2025). "HOTAIR interacts with EZH2 and is upregulated in a variety of cancers (breast, lung, colon and gastric)." (PMID 40868070, 2025). "PVT1 promotes cancer proliferation, cell cycle progression and migration via the EZH2 epigenetic route." (PMID 39912983, 2025). "More recently, EZH2 has gained significant attention for its potential as a therapeutic target for cancer therapies, particularly in lung cancers." (PMID 40310411, 2025). "In this review, drawing upon our comprehensive understanding of the factual underpinnings of EZH2's role in cancer, we aim to clarify the crucial importance of targeting EZH2 in cancer treatment." (PMID 40028035, 2025). "A significant proportion of glucose-induced genes were lncRNAs, many of which regulate EZH2, a histone methyltransferase known to drive dedifferentiation in cancer cells." (PMID 41301413, 2025). "Previous studies on the combination of HDAC inhibitors and EZH2 inhibitors in various cancers have largely overlooked the changes in H3K27me3 levels following HDAC inhibitor treatment." (PMID 40659662, 2025). "Our findings are consistent with previous studies with respect to the functional role of EZH2 inhibitors on epigenetic effect and limiting cell differentiation of HPV-associated cancers." (PMID 41614754, 2025). "As the diverse functions of EZH2 continue to be uncovered, it is imperative to have a precise understanding of its intricate and diverse roles to effectively target it in cancer therapy." (PMID 40028035, 2025).
cancer (continued). "Increasing numbers of studies have demonstrated that EZH2 participates in many diverse biological processes and control the expression of many downstream genes in different cancers." (PMID 39850359, 2025). "Pre-clinical studies showed that EZH2 inhibition increases the anti-cancer activity of sorafenib in HCC models." (PMID 40968252, 2025). "Overall, these findings suggest that squamocin is less neurotoxic than rotenone and represents an attractive candidate for targeting EZH2/MYC axis‐dependent cancers." (PMID 39823459, 2025). "Recent studies showed that USP7 interacts with Ezh2 and promotes its stabilization in cancer cells and that loss of USP7 leads to Ezh2 destabilization." (PMID 40247205, 2025). "Since EZH2 is often overexpressed in SWI/SNF-mutant cancers, it makes for a potential target for therapies, as is the case with EZH2 inhibitors, currently in clinical trials." (PMID 39941902, 2025). "Collectively, several transcription factors and RNAs cooperate to facilitate the elevated expression of EZH2 in cancer." (PMID 40028035, 2025). "In adult cancers, inhibiting EZH2, a component of PRC2, has been successful in restoring immunogenicity in adult cancers with ARID1A mutations 38,39." (PMID 40082458, 2025). "As an oncogenic driver in various cancers, EZH2 promotes tumorigenesis and sustains cancer stem cell maintenance." (PMID 41226409, 2025). "For instance, it has been reported that H3K27 acetylation can increase as a resistance mechanism in response to EZH2 inhibitor treatment in other cancer cells." (PMID 41007839, 2025). "Treatment of mice models with targeted polymers of nucleic acids against lncRNA HOTAIR, was found to reduce its expression and interaction with EZH2, leading to anti-cancer effect." (PMID 39912983, 2025). "The study also noted an overexpression of EZH2 a key epigenetic regulator that represses tumour suppressor genes and promotes cancer progression, particularly in aggressive subtypes such as triple-negative breast cancer." (PMID 40813389, 2025). "Enhancer of zeste homologue 2 (EZH2) and histone deacetylases (HDACs) are key epigenetic regulators of cancer progression." (PMID 40464712, 2025). "Studies on the human cancer genome have revealed high expression of EZH2 in various cancers, with involvement in different biological functions, including ferroptosis." (PMID 41372608, 2025). "EZH2 has been contemplated as a therapeutic target for several types of cancer, including BCC and cSCC." (PMID 40101298, 2025). "Research indicates that EZH2 serves as a pivotal regulator in regulating cancer cell immune response and mediates escape by downregulating immune activation genes, upregulating checkpoints, and creating an immunosuppressive TME." (PMID 40927709, 2025). "For instance, cancer cells with inactivating mutations in ARID1A become highly dependent on the opposing polycomb repressive complex 2 (PRC2) component, EZH2, creating a therapeutic vulnerability." (PMID 40940815, 2025). "In several cancers, including lung, colon, breast, pancreas, and prostate, overexpression of EZH2 plays two key roles: (a) modulation of innate and adaptive immune pathways and (b) regulation of stem cell self-renewal, differentiation, and lineage fate." (PMID 39946195, 2025). "While these findings suggest a relationship between EZH2 and RB1 across various cancers, direct evidence of EZH2's role in regulating RB1 expression remains limited." (PMID 40070134, 2025). "Enhancer of zeste homolog 2 (EZH2) is an essential epigenetic regulator of H3K27 histone methylation and is mutated or overexpressed in a wide variety of cancers." (PMID 39984702, 2025). "The clinical development of EZH2 inhibitors thus offers novel therapeutic strategies for a broad spectrum of diseases, including cancer, inflammatory disorders, and autoimmune diseases." (PMID 41326356, 2025).
cancer (continued). "Machine learning analysis pinpointed 14 feature genes, among seven were associated with cancer (NAT1, BIRC3, EZH2, MAD2L1, ATP2A3, HMGA1, and BST2)." (PMID 41255601, 2025). "Recent studies have also started designing EZH2-based dual inhibitors due to their synergistic antitumour effects with other cancer agents." (PMID 41614754, 2025). "The catalytic properties of EZH2 play a crucial role in cancer development and progression thus making it an attractive therapeutic target." (PMID 40959208, 2025). "Database searches indicated that NAT1, BIRC3, EZH2, MAD2L1, ATP2A3, HMGA1, and BST2 are cancer-associated genes." (PMID 41255601, 2025). "In conclusion, the targeting of histone PTMs, including HDACs and EZH2, represents a promising avenue for addressing drug resistance in cancer therapy." (PMID 40675967, 2025). "Such DCAF1-mediated EZH2 phosphorylation followed by nuclear localization led to elevated levels of H3K27me3 and altered expression of growth regulatory genes in cancer cells." (PMID 40289112, 2025). "Promising results from early-phase clinical trials in cancers such as epithelioid sarcoma and follicular lymphoma highlight the potential of EZH2 inhibitors in targeting CSC populations through epigenetic reprogramming." (PMID 40099195, 2025). "For example, inhibitors targeting EZH2, a histone methyltransferase, are under investigation for treating cancers with specific epigenetic alterations." (PMID 39982247, 2025). "To select putative PLUM regulated EZH2 targets involved in UPR-mediated chemoresistance, we focused on genomic loci exhibiting reduced H3K27me3 marks at the TSS of cancer associated genes." (PMID 40890111, 2025). "Targeting EZH2 with inhibitors offers potential for cancer therapy by reversing its epigenetic effects." (PMID 39083441, 2025). "An interesting finding is that the two subpopulations show differential sensitivity to the FDA-approved EZH2 inhibitor, and thus would likely have implications to cancer treatment." (PMID 40504770, 2025). "The resistance of TNBC to EZH2 inhibitors, despite high EZH2 expression, presents a substantional challenge in cancer therapy." (PMID 41413688, 2025). "Tazemetostat (Tazverik), a U.S. FDA-approved oral EZH2 inhibitor, is already in clinical use for the treatment of specific cancers." (PMID 40959108, 2025). "Several recent studies suggest that EZH2 modulates autophagy, a crucial cellular degradation process that maintains homeostasis and influences cancer cell survival under stress." (PMID 40314246, 2025). "Elevated EZH2 expression has been observed in various cancers, including breast, prostate, lung, and thyroid, and is linked to poor prognosis." (PMID 40042761, 2025). "These cells are homozygous null mutants for the CDKN2A locus, which makes them a good model to study the CDKN2A-independent function of EZH2 in cancer." (PMID 39174513, 2024). "The regulatory effects of ncRNA binding on PRC2 core components, especially on EZH2 as the enzymatic catalytic subunit of the complex, have significant therapeutic potential in different cancers." (PMID 38473229, 2024). "Further, MEG3 exerted anti-cancer effects by mediating ubiquitination of EZH2, thereby leading to its degradation." (PMID 38473229, 2024). "EZH2 has been shown to be involved in cancer cells invasion and migration, important hallmarks of malignant tumors." (PMID 39204206, 2024). "Significant preclinical data support the potential of EZH2 inhibition in pediatric cancer treatment." (PMID 39766049, 2024). "For these reasons PRC2’s catalytic subunit EZH2 was considered in the first place as an attractive drug target for cancer therapy." (PMID 38242973, 2024). "In the past decade, researchers have developed several inhibitors targeting EZH2, an important protein involved in cancer progression." (PMID 38600608, 2024).
cancer (continued). "DPYSL5 overexpression also led to increased mRNA expression of Nanog, SOX2, NSE, CGA, and ASCL1, suggesting that cells achieve characteristic of neuron-like cancer progenitor cells, possibly through the activation of EZH2." (PMID 38238517, 2024). "Clinical trials have reported on EZH2 inhibitors’ safety and efficacy in cancer, but their putative use in cardiometabolic disease has not been explored." (PMID 38580969, 2024). "This silencing is mediated by enhancer of zeste homolog 2 (EZH2), a polycomb group protein implicated in cancer progression." (PMID 39334719, 2024). "The discovery of the genomic feature related to EZH2 through the KL-Relevance approach highlights its impact on drug responses and potential involvement in drug resistance in cancer cells." (PMID 39304771, 2024). "EZH2 has also been found to play an essential role in tumorigenesis, progression, and metastasis of cancer, and its overexpression has been observed in various types of cancer." (PMID 39497715, 2024). "MALAT1 has been identified to bind with Enhancer of zeste homolog 2 (EZH2) and control the downstream genes expression through modifying histone methylation in cancer cells." (PMID 39681821, 2024). "It has been demonstrated that EZH2 interacts with the NF-κB transcription factors, RelA and RelB, to activate pro-inflammatory genes in several cancer types, suggesting that the NF-κB target gene signature is positively regulated by EZH2." (PMID 39204206, 2024). "The duality of EZH2 over- and underexpression, the temporal differentiation of expression, and its extensive presence in various lines of cancer alludes to its a high potential for research for pharmacological interventions." (PMID 39768352, 2024). "In the context of TNBC, EZH2 plays a pivotal role in its progression by promoting the migration and invasion of cancer cells through the regulation of the TIMP2-MMP-2/-9 pathway." (PMID 39120328, 2024). "It is emerging that EZH2 strongly contributes to driving cancer cells’ immunoediting and immune escape." (PMID 39769907, 2024). "To date, the U.S. FDA has approved two small-molecule inhibitors: tazemetostat (EPZ-6438) and valemetostat (DS-3201b), which target EZH2 or both EZH1 and EZH2 for cancer therapy." (PMID 39620228, 2024). "Signaling pathways, including MEK-ERK1/2, pSTAT3, and MYC signaling were demonstrated to activate EZH2 transcription in different cancer types." (PMID 38339397, 2024). "EZH2 inhibition therapy has shown promising results in multiple cancer entities, with ongoing research exploring its potential in other malignancies." (PMID 40135141, 2024). "As cells mature and differentiate, EZH2 loses its functional importance, making EZH2 a cancer cell-specific therapeutic target." (PMID 38254784, 2024). "Aberrant EZH2 activity not only disrupts embryonic development but also impairs tissue homeostasis contributing to cancer, kidney, neurological, metabolic, and cardiovascular diseases." (PMID 38580969, 2024). "Double hybrid molecule 5, targeting HDAC and EZH2 inhibits proliferation and kills cancer cells at low micromolar concentrations in several cancer cell types." (PMID 38225241, 2024). "In contrast to the action of EZH2 in developing embryonic cells, where it exerts transcriptional repression of genes involved in cell differentiation, overexpressed EZH2 in cancer cells induces growth-related gene expression in a PRC2-independent manner." (PMID 38664825, 2024). "For example, the enhancer of zeste homolog 2 (EZH2) is a methyltransferase that tri-methylates histone 3 lysine 27 (H3K27me3), and EZH2 is overexpressed in multiple types of cancer." (PMID 39409910, 2024). "Combination immunotherapy can block the immune suppression effects of EZH2 inhibitors and exert a combined anti‐cancer effect." (PMID 38520088, 2024).